MFN2 (mitofusin 2)
Diseases named in the same sentence as MFN2 in open-access papers (continued):
Sharing a sentence is not in itself a finding about the gene and the disease.
female infertility (6 papers, 2019 to 2025). Diminished or absent ability of a female to achieve conception. "Targeted deletion of MFn2 protein in the mitochondrion causes a decline in oocyte maturation and female infertility, with impaired oocyte granulosa cell communication, resulting in aberrant follicular development especially at the secondary follicle stage." (PMID 38561673, 2024). "Deletion of the MFN2 gene in mouse oocytes leads to mitochondrial dysfunction and female subfertility associated with impaired oocyte maturation and follicular development." (PMID 37091980, 2023). "Oocytes missing mitofusin 2 (MFN2) led to female infertility because it is an important protein causing mitochondria fusion." (PMID 36496972, 2022). "Targeted deletion of Mfn2 in oocytes resulted in mitochondrial dysfunction and female subfertility associated with impaired oocyte maturation and follicle development." (PMID 31204316, 2019). "Similarly, reduced MFn2 expression has been reported to contribute to defective follicular maturation and female infertility, and this defect have been associated with mitochondrial dysfunction." (PMID 38561673, 2024). "In this study, we uncovered that oocyte specific deletion of Mfn2 results in female subfertility due to impaired oocyte maturation and follicular development." (PMID 31204316, 2019). "Our findings demonstrate that absence of MFN2 in oocytes results in female subfertility associated with impaired folliculogenesis and oogenesis." (PMID 31204316, 2019). "Mitofusin 2 (MFN2) is a key protein involved in mitochondrial fusion, causing oocytes lacking MFN2 that contributed to female infertility." (PMID 35120535, 2022).
ischemic stroke (6 papers, 2021 to 2025). A stroke disorder caused by obstruction of blood flow to the brain, due to thrombotic (local blood clot formation) or embolic (due to a blood clot or other material traveling from another site) event. "The downregulation of Mfn2 by Mul1 increased the fragmented mitochondria concomitant with mitochondrial dysfunction and cell death in ischemic stroke." (PMID 36531208, 2022). "The downregulation of Mfn2 by Mul1 exacerbated mitochondrial dysfunction and cell death after ischemic stroke." (PMID 36531208, 2022). "The downregulation of Mfn2 by Mul1 increased the fragmented mitochondria concomitant with the mitochondrial dysfunction and cell deaths after the experimental ischemic stroke." (PMID 36531208, 2022). "During the acute phase of ischemic stroke, increased mitophagy was shown to be accompanied by the enhancive fusion markers Mfn1 and Mfn2 on astrocytes." (PMID 35153669, 2021). "The MFN2 expression has been studied in ischemic stroke in recent years." (PMID 35571256, 2022). "The change of the MFN2 expression in ischemic stroke may provide a research direction for the treatment of ischemic stroke." (PMID 35571256, 2022). "This phenomenon represents Mfn2 as a potentially anti-apoptotic factor after ischemic stroke." (PMID 35153669, 2021). "Both MFN2 and DRP1 have been reported as MUL1 targets, whose levels also concomitantly change in other pathological conditions, such as ischemic stroke." (PMID 37051468, 2023). "In consistent with previous studies, the present study showed that the expression levels of MFN1 and MFN2 were significantly elevated after silencing ATF3 in OGD/R-treated cells and ischemic stroke rats, suggesting the protective effect of silencing ATF3 on mitochondrial homeostasis." (PMID 40621504, 2025).
Madelung's disease (6 papers, 2020 to 2025). "The signature of epithelial-mesenchymal transition (EMT) was the most strongly down-regulated set in mouse BAT and WAT, and was also previously found to be downregulated in overgrown human WAT in MFN2-associated multiple symmetric lipomatosis." (PMID 36722855, 2023). "Of note, human syndromes such as multiple symmetrical lipomatosis (Madelung’s disease), caused by mutations in MFN2, appear chiefly to lower insulin sensitivity." (PMID 32894309, 2020).
amyotrophic lateral sclerosis (5 papers, 2021 to 2026). Amyotrophic lateral sclerosis (ALS) is a neurodegenerative disease characterized by progressive muscular paralysis reflecting degeneration of motor neurons in the primary motor cortex, corticospinal tracts, brainstem and spinal cord. "This study investigates the prevalence of rare, non-synonymous MFN2 variants within an Italian cohort of amyotrophic lateral sclerosis patients, who have been extensively investigated, enhancing our knowledge of the underlying phenotypic spectrum." (PMID 39315308, 2024). "This study examines the clinical and genetic characteristics of an Italian cohort of amyotrophic lateral sclerosis patients with rare, non-synonymous MFN2 mutations." (PMID 39315308, 2024). "Although not consolidated yet, there is a growing body of evidence suggesting an association between variants in the MFN2 and the amyotrophic lateral sclerosis/frontotemporal dementia spectrum." (PMID 39315308, 2024). "In conclusion, the present cohort, together with findings from other works, suggests that MFN2 variants may play a role in amyotrophic lateral sclerosis pathology, highlighting the relevance of mitochondria and MFN2 in neuronal health." (PMID 39315308, 2024). "However, a few cases of amyotrophic lateral sclerosis and amyotrophic lateral sclerosis/frontotemporal dementia phenotypes with concomitant MFN2 mutations have been previously reported." (PMID 39315308, 2024). "However, to the best of our knowledge, this is the first study to provide a clinical, neurophysiological and molecular characterization of multiple patients affected by amyotrophic lateral sclerosis harbouring MFN2 variants and the largest work to assess their prevalence." (PMID 39315308, 2024). "A group of patients (n = 385) diagnosed with amyotrophic lateral sclerosis at our Neurology Units between 2008 and 2023 underwent comprehensive molecular testing, including MFN2." (PMID 39315308, 2024). "Different lines of evidence might suggest the possibility of a link between MFN2 and amyotrophic lateral sclerosis on both molecular and cellular levels." (PMID 39315308, 2024). "From this point on, these individuals will be referred to as MFN2-amyotrophic lateral sclerosis." (PMID 39315308, 2024). "Here, we retrospectively reviewed our cohort of 385 amyotrophic lateral sclerosis patients to investigate the prevalence of rare, non-synonymous MFN2 variants." (PMID 39315308, 2024). "None of the MFN2-amyotrophic lateral sclerosis patients tested positive for the pathogenic C9orf72 gene expansion, nor did they exhibit mutations in the SOD1 gene or the known mutational hotspots of the TARDBP (exon 6) and FUS (exons 13-14-15) genes." (PMID 39315308, 2024).
Charcot-Marie-Tooth disease type 2 (5 papers, 2006 to 2019). A Charcot-Marie-Tooth disease characterized by abnormalities in the axon of the peripheral nerve cell. "Mutations in the mitochondrial GTPase mitofusin 2 (MFN2) cause Charcot-Marie-Tooth disease type 2 (CMT2A), a form of peripheral neuropathy that compromises axonal function." (PMID 30911005, 2019). "We confirmed a significant role of mutations in MFN2 in the pathogenesis of Charcot-Marie-Tooth disease type 2." (PMID 16762064, 2006). "Mfn2 was firstly discovered as a mutated fusion protein in the outer mitochondrial membrane in Charcot-Marie-Tooth type 2 neurodegeneration, even if it may function also as a mediator of autophagy." (PMID 29206172, 2017).
nonalcoholic steatohepatitis (5 papers, 2020 to 2025). "In addition to regulating lipid droplets and MERCs, MFN2 was recently shown to have a direct role in transferring phosphatidylserine from the ER to mitochondria, a function implicated in non-alcoholic steatohepatitis." (PMID 38274408, 2021). "In nonalcoholic steatohepatitis, mitotic protein 2 (Mfn2) promotes ferroptosis by interacting with inositol demand enzyme (IRE1α) to promote the production of 5-HETE and ferroptosis and hepatitis is significantly alleviated by reducing the content of 5-HETE." (PMID 40448227, 2025). "A previous study showed that Mfn2 binds to PS and favors the translocation of PS to mitochondria, thereby ameliorating nonalcoholic steatohepatitis in mice." (PMID 39329159, 2024). "In fact, reduced Mfn2 expression was detected in liver biopsies from patients with nonalcoholic steatohepatitis." (PMID 32331285, 2020).
osteosarcoma (5 papers, 2017 to 2024). A usually aggressive malignant bone-forming mesenchymal neoplasm, predominantly affecting adolescents and young adults. "Further investigation is needed to fully understand the underlying mechanisms of MFN2 in tumor immunity and its potential as a therapeutic target in osteosarcoma." (PMID 37405988, 2023). "The expression level of MFN2 is increased in osteosarcoma, and it can inhibit the immune system in osteosarcoma TIM." (PMID 38800967, 2024). "In this study, a total of six key cuproptosis-mitochondrion genes (FDX1, TOMM20, NDUFB9, COX11, MFN2 and ATP6V1E1) associated with prognosis of osteosarcoma were finally identified." (PMID 37405988, 2023). "A total of six cuproptosis-mitochondrion genes (FDX1, COX11, MFN2, TOMM20, NDUFB9 and ATP6V1E1) were identified to be associated with the prognosis of osteosarcoma." (PMID 37405988, 2023). "Among them, FDX1, TOMM20 and NDUFB9 were associated with poor survival of osteosarcoma while COX11, MFN2 and ATP6V1E1 predicted good." (PMID 37405988, 2023). "In the present study, we further confirmed that Tan IIA indeed reduced the levels of Mfn-1, Mfn-2 and Opa-1 and increased the levels of Drp-1 in both osteosarcoma 143B cells and 143B cell xenograft mice." (PMID 28106052, 2017). "Therefore, MFN2 may impact the immune function of osteosarcoma and thus lead to a poorer prognosis." (PMID 37405988, 2023). "The expression of FDX1, COX11, MFN2, TOMM20 and NDUFB9 at mRNA level was elevated in osteosarcoma cells compared with normal osteoblast hFOB1.19." (PMID 37405988, 2023). "Mitofusin 1 (Mfn1) when phosphorylated by ERK1/2 inhibits mitochondrial fusion while mitofusin 2 (Mfn2) when phosphorylated by JNK becomes a substrate for the proteasome and promotes the fragmentation of mitochondria in human osteosarcoma cells." (PMID 33498615, 2021). "Finally, it was experimentally verified that the expression of FDX1, COX11, MFN2, TOMM20 and NDUFB9 at mRNA levels was elevated in osteosarcoma." (PMID 37405988, 2023). "However, we are not aware of any study on the immunological aspects of FDX1, TOMM20, NDUFB9, COX11, MFN2 and ATP6V1E1 in osteosarcoma for the time being, which is a direction we need to study subsequently." (PMID 37405988, 2023).
Anxiety (4 papers, 2021 to 2025). Intense feelings of nervousness, tension, or panic often arise in response to interpersonal stresses. "Mfn2 is usually considered a fusion-related protein, but it also plays critical role in mediating mitochondrial contact points with the endoplasmic reticulum independent of fusion and its expression in NAc has been linked to anxiety-like behaviors." (PMID 34867530, 2021). "Hence, regulating MFN2-mediated mitochondrial function and neuronal traits emerges as a key mechanism governing anxiety and motivated behaviors, providing a promising therapeutic target for managing anxiety and depression phenotypes." (PMID 38916735, 2024).
Atrophy (4 papers, 2021 to 2024). Any weakening or degeneration, especially through lack of use. "Mitochondria have double membranes, and their fusion needs fusion of both outer and inner membranes; while optic atrophy mediates inner membrane fusion, mitofusins 1 and 2 (Mfn1 and Mfn2) help in outer membrane fusion, and among the two mitofusins, Mfn2 is considered essential for fusion." (PMID 35399705, 2022). "Similarly, a recent study demonstrated that overexpression of MFN2 in skeletal muscle of aged mice led to slight muscle hypertrophy, indicating that MFN2 overexpression may be a viable approach to mitigate age-related muscle atrophy." (PMID 38654156, 2024). "Mitochondrial fusion is regulated by mitofusin 1 (MFN1), mitofusin 2 (MFN2), and optic atrophy (OPA1)." (PMID 33716776, 2021).
brain injury (4 papers, 2023 to 2025). Acute and chronic (see also brain INJURIES, CHRONIC) injuries to the brain, including the cerebral hemispheres, CEREBELLUM, and brain STEM. "The epigenetic regulation of MFN2, including DNA methylation, has been studied in relation to mitochondrial dysfunction caused by brain trauma, indicating that hypermethylation of the MFN2 gene promoter can downregulate its decreased leading to subsequent mitochondrial dysfunction." (PMID 41456957, 2025). "A recent study has shown that Mfn2 expression in the brain can be modified by DNA methylation and can play a critical role in repeated mild traumatic brain injuries-induced persistent cognitive deficits." (PMID 37373839, 2023).
Cachexia (4 papers, 2012 to 2023). Severe weight loss, wasting of muscle, loss of appetite, and general debility related to a chronic disease. "Moreover, MFN2-mediated fusion re-establishment in mice with cachexia attenuates skeletal muscle loss." (PMID 38001815, 2023). "During the development of cachexia in ApcMin/+ mice, which is a genetic model of colon cancer, protein expression of Mfn2 was decreased in skeletal muscle." (PMID 34427401, 2021). "We report that the expression of both Mfn1 and Mfn2 proteins are repressed during pre-cachexia, and this is one of the earliest alterations in protein expression related to oxidative metabolism we have found in skeletal muscle." (PMID 22769563, 2012). "IL-6 receptor antibody administration after the onset of cachexia improved mitochondrial content, PGC-1α, Mfn1/Mfn2 and FIS1 protein expression." (PMID 22769563, 2012). "Mitochondrial content was not reduced during the initial development of cachexia, while muscle PGC-1α and fusion (Mfn1, Mfn2) protein expression was repressed." (PMID 22769563, 2012).
colorectal cancer (4 papers, 2018 to 2025). A primary or metastatic malignant neoplasm that affects the colon or rectum. "In liver, lung, breast, and colorectal cancers, GTPase mitofusin-2 (Mfn2) located at the outer membrane of the mitochondria is able to restore cell death by inhibiting the mTORC2–AKT axis." (PMID 35159351, 2022). "Relationship between circ-MFN2 expression and clinicopathologic features of colorectal cancer patients." (PMID 34093664, 2021). "Previous investigations have shown that Mfn2 overexpression results in a cell cycle arrest at the G2/M phase and induces caspase-independent apoptosis in colorectal cancer cells." (PMID 30410558, 2018). "However, the role of circ-MFN2 in colorectal cancer (CRC) is unclear." (PMID 34093664, 2021).
Encephalopathy (4 papers, 2011 to 2017). Encephalopathy is a term that means brain disease, damage, or malfunction. "Boaretto and co-workers reported on an Italian family in which a new splice-site MFN2 gene mutation was associated with fulminant fatal encephalopathy in three individuals." (PMID 28076385, 2017). "The third de novo mutation, a c.250A > G (p.Lys84Glu) substitution in the MFN2 gene, was identified in a 12 year old child with severe mixed (axonal and demyelinating) polyneuropathy, scoliosis, contractures, respiratory difficulties and encephalopathy." (PMID 24444136, 2014). "MFN2 c.1392+2T>C, a mutation that affects the donor splice site of intron 13, was recently identified in a family with severe CMT2 and fatal encephalopathy." (PMID 22206013, 2011). "We will then integrate MFN2, responsible for CMT2A2 [MIM:609260], and DNM1L associated with encephalopathy with lactic acidosis [MIM:603850]." (PMID 22200116, 2011).
extrahepatic cholestasis (4 papers, 2013 to 2021). Impairment of the bile flow caused by an obstruction in the portion of the bile duct system located outside of the liver. "In light of the profound impact of Mfn2 on mitochondria function, exploring the mechanism underlying the function of Mfn2 in extrahepatic cholestasis is an important area of clinical research." (PMID 23755235, 2013). "Taken together, these findings suggest that Mfn2-mediated mitochondrial fusion is an essential mechanism underlying GCDCA-induced hepatotoxicity in extrahepatic cholestasis." (PMID 23755235, 2013). "Taken together, these findings indicate that the loss of Mfn2 may play a crucial role the pathogenesis of the liver damage that is observed in patients with extrahepatic cholestasis." (PMID 23755235, 2013). "In some patients with extrahepatic cholestasis, Mfn2 expression in the liver is decreased, suggesting that Mfn2 plays an important role in regulating lipid metabolism and mitochondrial function." (PMID 34307357, 2021). "Endogenous MFN2 expression has been reported to decrease in patients with extrahepatic cholestasis characterized by elevated levels of toxic bile acids, and also in subjects with NASH." (PMID 34073868, 2021). "We then investigated the effects of Mfn2 on mitochondrial metabolism in liver tissue from patients with extrahepatic cholestasis and the possible protective effects of Mfn2 overexpression in the L02 cell lines." (PMID 23755235, 2013). "In this study, we first investigated the expression levels of Mfn2 in samples from patients with extrahepatic cholestasis and in the hepatocyte cell line L02 treated with GCDCA." (PMID 23755235, 2013). "Furthermore, patients with extrahepatic cholestasis show low hepatic MFN2, and glycochenodeoxycholic acid, the main toxic component of bile acid in these patients, represses MFN2 in human liver cells." (PMID 34073868, 2021). "Interestingly, endogenous expression of the mitochondrial fusion protein Mfn2 was shown to be decreased in patients with extrahepatic cholestasis, and expression of Mfn2 decreased significantly when fetal hepatocyte L02 cells were exposed to GCDC." (PMID 34485975, 2021). "Taken together, our in vitro studies suggest that there may be two biological roles for Mfn2 during the progression extrahepatic cholestasis." (PMID 23755235, 2013). "Therefore, the aims of this study were to evaluate the expression levels of Mfn2 in liver samples from patients with extrahepatic cholestasis and to investigate the role Mfn2 during bile acid induced injury in vitro." (PMID 23755235, 2013). "Endogenous Mfn2 expression decreased in patients with extrahepatic cholestasis." (PMID 23755235, 2013). "To explore the mechanism of bile acid-induced hepatotoxicity during extrahepatic cholestasis, we treated L02 cells with GCDCA and then assayed the Mfn2 expression and mitochondrial function." (PMID 23755235, 2013). "Specifically, Mfn2 may serve as a therapeutic target for the development of novel treatments to prevent liver damage in patients with extrahepatic cholestasis." (PMID 23755235, 2013).
glaucoma (4 papers, 2009 to 2023). Increased pressure in the eyeball due to obstruction of the outflow of aqueous humor. "Nivison examined a protein (mitofusin 2) involved in mitochondrial biogenesis, maintenance, and transport in retinal ganglion cells in mice with glaucoma; they observed that degenerated mitofusin 2 accumulates with age in retinal ganglion cells during glaucoma progression." (PMID 35327479, 2022). "The objective of this study was to investigate association of several genes that have not been subject to an association study with glaucoma cases so far but might be functionally linked to glaucoma pathogenesis (RDX, SNX16, MFN1, MFN2, PARL, SOD2)." (PMID 19754948, 2009).